HP (haptoglobin)
Diseases named in the same sentence as HP in open-access papers (continued):
Sharing a sentence is not in itself a finding about the gene and the disease.
cancer (continued). "The lack of association between inflammatory markers and specific cancer risk was further shown when we investigated serum CRP, leukocytes, albumin, and haptoglobin in relation to prostate cancer." (PMID 26284119, 2015). "Fucosylated alpha-fetoprotein (AFP) is widely used in the diagnosis of hepatocellular haptoglobin have also been found in sera of patients with various carcinomas." (PMID 24255851, 2013). "This review describes the role of fucosylated haptoglobin as a cancer biomarker, and discusses the possible biological role of fucosylation in cancer development." (PMID 24970126, 2012). "The ectopic expression of haptoglobin is observed in special conditions such as infections, inflammation and cancer." (PMID 24970126, 2012). "High levels of fucosylated haptoglobin have also been found in sera of patients with various carcinomas." (PMID 24970126, 2012). "The level of galectin-1 bound haptoglobin in the cancer sera was on average about twice as high (range 0.6–4 fold) compared to the average for control sera, and confirmed by SDS-PAGE." (PMID 22028908, 2011). "This suggests that this is a major regulatory step in the scavenging of haemoglobin by haptoglobin, and that this regulation can be dramatically altered in cancer." (PMID 22028908, 2011). "In conclusion, galectin-1 detects a new type of functional biomarker for cancer: a specific type of glycoform of haptoglobin, and possibly other serum glycoproteins, with a different function after uptake into tissue cells." (PMID 22028908, 2011). "The present results demonstrate that a significant fraction of human serum α-2-macroglobulin, IgM and haptoglobin, bind to galectin-1 and that the total amount of galectin-1-binding glycoproteins can be 2–3 times larger in sera of some cancer patients." (PMID 22028908, 2011). "A previous study has shown that there are high levels of an abnormally-fucosylated form of haptoglobin (FHp) in the blood of cancer patients." (PMID 1892771, 1991). "Furthermore, cancer‐related glycosylation changes in haptoglobin have been extensively studied in several cancers, including liver and pancreatic cancers." (PMID 40589150, 2025). "Haptoglobin has increasingly been recognised for its involvement in cancer biology." (PMID 40606553, 2025). "Additionally, haptoglobin-conjugated nanoparticles and liposomes are under development for targeted drug delivery to inflamed tissues or cancer sites, aiming to maximise therapeutic efficacy while minimising systemic adverse effects." (PMID 40606553, 2025). "Haptoglobin modulates inflammatory responses, which are crucial in the pathogenesis of cancer." (PMID 40606553, 2025). "One of the primary functions of haptoglobin in cancer is its interaction with the immune system." (PMID 40606553, 2025). "The abnormal glycosylation of haptoglobin has been documented to assist cancer diagnosis." (PMID 38575942, 2024). "From all serum glycoproteins recently reported as potential cancer serum markers, haptoglobin seems to be a promising glycobiomarker, in which the strategy of combined protein quantification and glycan characterization could be employed." (PMID 37455827, 2023). "In our previous studies, lectin-antibody enzyme-linked immunosorbent assay (ELISA) was used to measure serum fucosylated haptoglobin (Fut-Hp) levels and revealed significantly increased serum Fut-Hp levels in several types of cancer and inflammatory bowel diseases." (PMID 37821468, 2023). "We analyzed the expression of CCR2, a key chemotactic receptor on monocytes responsible for their recruitment into tumor mass, and CD163, a clearance receptor for hemoglobin-haptoglobin complex, which expression on TAMs correlates with tumor growth and metastasis in various cancers including CRC." (PMID 36733385, 2022).
cancer (continued). "Haptoglobin is an acute phase protein which is mainly synthesized in liver and is reported to be overexpressed in various types of cancers including GBC and reported to promote cell proliferation, migration and invasion, which implies its role in pathophysiological process of GBC." (PMID 36505879, 2022). "Furthermore, HP expressions combined with other serum markers, would be of reference value to the early diagnosis of relevant cancers and of some guiding significance in terms of treatment and prognosis." (PMID 35860021, 2022). "The increased expression of HP is frequently detected in various cancers." (PMID 34178453, 2021). "In addition, compared to liver metastatic cancer tissues, CP, HP, TF, and SERPINA5 were upregulated in normal liver tissues, while the expression CDH2 and SPARCL1 did not exhibit significant differences between the two tissues." (PMID 34422629, 2021). "Therefore, inhibition of some of these stress-response proteins such as heat shock proteins, complement, haptoglobin or fibrinogen, has recently been proposed as a promising new direction for cancer treatment." (PMID 33917524, 2021). "The combination of the haptoglobin, ceruloplasmin and C6 did not yield a better diagnostic efficacy for low grade cancer patients compared to individual biomarker alone (data not shown)." (PMID 32620920, 2020). "Finally, the positive correlation between the circulating HP levels and its muscle mRNA in cancer patients, supports the contribution of the skeletal muscle to the HP circulating concentrations." (PMID 33142864, 2020). "Out of 30 samples, Haptoglobin marker was positive in 21 cancer and normal samples, respectively." (PMID 32232956, 2020). "We found that HP may serve as a biomarker for cancer progression based on several independent datasets." (PMID 28771541, 2017). "Cancer‐induced changes in the glycosylation status of haptoglobin, α1‐acid glycoprotein, and α1‐anti‐chymotrypsin, have been fully investigated, however, relatively little has been investigated pertaining to the glycosylation of serum major resident proteins such as immunoglobulins." (PMID 26880719, 2016). "This change in haptoglobin N-glycosylation could affect extracellular matrix interactions and/or contribute to immunosuppression of lymphocytes for promoting cancer." (PMID 25484625, 2014). "The use of a glycomic approach, has allowed the identification of a number of tumor marker candidates, finding that fucosylated haptoglobin in sera could be a possible tumor marker for several kinds of cancer types." (PMID 24576319, 2014). "Although the liver is the major source of serum HP, it is also secreted by some cancer cells." (PMID 24066001, 2013). "Increased fucosylated haptoglobin levels have been observed in several types of cancer (20–40%)." (PMID 24970126, 2012). "These other glycans may also be part of a cancer related glycan profile, if, for example, the haptoglobin comes from cancer cells, as proposed, or liver cells indirectly affected by the presence of cancer elsewhere in the body." (PMID 22028908, 2011). "On average 30% of haptoglobin from healthy sera take this route, whereas for cancer sera it may be up to 80%." (PMID 22028908, 2011). "Specific cancer induced forms of common serum glycoproteins, such as transferrin or haptoglobin that are synthesized mainly in the liver, have also been observed and may serve as markers of the physiological effects of the cancer." (PMID 22028908, 2011). "The five proteins that met our criteria for an increase in relative abundance in the cancer compared to the control were haptoglobin (HAPT), orosomucoid-1 (ORM1), leucine-rich alpha-2-glycoprotein-1 (LRG1), alpha-1 antichymotrypsin (AACT), and fibrinogen-alpha (FGA)." (PMID 20546617, 2010).
cancer (continued). "Components include platelet count, creatinine level, evidence of hemolysis (high reticulocyte count and indirect bilirubin and undetectable haptoglobin), and other associated conditions (lack of active cancer, solid organ, or hematopoietic stem cell transplant)." (PMID 40704299, 2025). "Interestingly, advanced cancer tissue may become unhospitable to HP, thus justifying its disappearance or substitution by other “passenger” bacteria, including F. nucleatum." (PMID 37174049, 2023). "For example, specific biomarkers, such as haptoglobin and leukocytes, which were shown to have positive associations with the risk of HNC in the time-to-event analysis, demonstrated higher-than-expected levels during the 30-year period prior to cancer diagnosis among individuals with HNC." (PMID 37876941, 2023). "Additionally, CATB (Cathepsin B) was previously reported as a potential candidate cancer biomarker in HCC, HPT (haptoglobin) was reported to associate with tumor progression in HCC, while POSTN (periostin) was reported as a marker for malignant transformation of hepatocytes." (PMID 30598095, 2018). "While haptoglobin is typically anti-inflammatory, glycosylation site alterations have been identified in RA and other diseases such as cancer; the ability of glycosylation to alter protein function and immunogenicity suggests that glycosylation alterations may serve pathogenic roles." (PMID 27067270, 2016). "Furthermore, fucosylated haptoglobin was also identified as a marker for various types of cancer." (PMID 27136596, 2016). "Both the IgM and haptoglobin concentrations were similar in cancer compared to control sera, but the percentage bound to galectin-1 was lower for IgM and higher for haptoglobin: about 50% (range 20–80) in cancer sera and about 30% (range 25–50) in healthy sera." (PMID 22028908, 2011). "Therefore, previous studies and the present study may have detected overlapping sets of cancer related haptoglobin glycoforms." (PMID 22028908, 2011). "Functional enrichment analysis demonstrated the involvement of these differentially expressed genes in the “haptoglobin-hemoglobin complex,” while KEGG pathway analysis indicated their participation in the “Proteoglycans in cancer” pathway." (PMID 38655066, 2024). "Results show that SPARCL1, CDH2, CP, HP, TF and SERPINA5 were all significant downregulated in cancer tissues (p < 0.05)." (PMID 34422629, 2021). "LRFN4, ADAMTS12, MCEMP1, HP and MUC15 are all cancer-related biomarkers, and all of them can also be used in judgment of cancer incidence in an independent manner." (PMID 32908454, 2020). "The concentrations of serum amyloid A (SAA), haptoglobin and serum amyloid protein (SAP) were significantly increased in tumour-bearing mice at 5 and 6 weeks following cancer cell inoculation." (PMID 29788918, 2018). "Several other acute-phase response proteins were also elevated towards diagnosis (e.g., HP, ORM1, ORM2, CRP, SERPINF2), presumably due to a host systemic inflammatory response—a known prognostic indicator in cancer patients." (PMID 29232830, 2017). "Due to its immunogenic and immunomodulatory properties, HP-NAP has been used for developing vaccines against H. pylori infection and new drugs for cancer therapy." (PMID 25880121, 2015). "We also found that individuals with HNC exhibited higher-than-expected levels of haptoglobin, leukocytes, sedimentation rate, and monocytes, as well as lower-than-expected levels of lymphocytes in % and LMR, during the 30-year period prior to cancer diagnosis." (PMID 37876941, 2023). "Thus, recombinant HP-NAP, as a potent immune modulator, is a promising therapeutic agent for the treatment of various types of cancers." (PMID 36613542, 2022). "We found 16 proteins including HP, PKM, ANXA2, THBS1 that are differentially abundant in GBC tissue (literature search and unpublished data from our lab), in plasma and plasma-derived EVs from GBC or other cancer patients." (PMID 36505879, 2022).
cancer (continued). "Other markers (Alpha-1-acid glycoprotein 2 (ORM2), Alpha-1B-glycoprotein (A1BG), Haptoglobin (HP), and Leucine-rich alpha-2-glycoprotein (LRG1), etc.)were found to create an ambiguous core involved in cancer development but also to exactly promote tumor progression in the early stages." (PMID 32023884, 2020). "Last, the exact mechanism of haptoglobin for cancer's tumorigenesis and progression was not clear, by now." (PMID 27248178, 2016). "The principal component scores of IgG‐SNA‐1, IgG‐WGA, haptoglobin‐SNA‐1, and PSA in the two‐dimensional X‐Y plot clearly segregated the cancer patients, the BPD patients and the normal subjects, which proves the validity of SNA‐1 and WGA as independent clinical markers for prostate diseases." (PMID 26880719, 2016). "The hepatic APR was not induced with cancer alone, as liver haptoglobin levels were comparable to the healthy C57BL/6 mice." (PMID 25789991, 2015). "Accumulated data suggested the usefulness of serum HP, either its level or modifications, as a biomarker for cancer diagnosis irrespective of cancer type." (PMID 24497876, 2014). "It should be pointed out that our mass spectrometry analysis does not necessarily distinguish between specific isoforms of the same protein and we cannot rule out the presence of “cancer-specific” isoforms of proteins such as haptoglobin." (PMID 21589862, 2011). "Both haptoglobin and its phenotype have been described previously in relation to various diseases (including cancer), a finding which is not surprising in view of its biology." (PMID 19108738, 2008). "This score's main determinants are platelets < 30,000/uL, presence of hemolysis (reticulocytes >2.5%, total bilirubin >2.0 or decreased haptoglobin), absence of active cancer, absence of stem cell or organ transplant, mean corpuscular volume < 90 fL, INR of <1.5, and Cr of < 2.0 mg/dL." (PMID 39618627, 2024). "HP-NAP may act as a variety of therapeutic agents, including a component of vaccines against H. pylori infection, a vaccine adjuvant, a drug candidate against allergic diseases, and an immunotherapeutic agent for cancer." (PMID 36613542, 2022). "The mRNA expression of APPs, haptoglobin and serum amyloid A, was not altered by cancer." (PMID 25789991, 2015). "Therefore, this study aimed to investigate whether the quantitative amount of Peroxiredoxin‐2 proteins that are candidates of tumor suppressor role as well as Haptoglobin and Alpha‐1 antitrypsin in patients with NSCLS can be biomarker candidate to early diagnosis of this cancer." (PMID 32232956, 2020). "In another study, Ang and colleagues compared the serum concentration of haptoglobin (Hp) and its glycoforms in patients with HCC and patients with chronic liver diseases (CLD) without cancer using glycosylation-specific lectins and 2D-PAGE." (PMID 33198323, 2020). "This suggests that the amount of O-linked sialylated haptoglobin contributing to the N-linked sialylated haptoglobin in SNA enrichment process is very low and it may not have a major impact in the determination of sialylation differences at the glycopeptides level between normal and cancer." (PMID 22856521, 2012).
tumor (79 papers, 1991 to 2026). "Among the seven potential footrot-associated proteins, haptoglobin precursor, afamin precursor, apolipoprotein-D have been reported as tumor biomarkers." (PMID 23418487, 2013). "Collectively, highly expressed haptoglobin results in a high hemoglobin/iron existence and raises the possibility of a causative involvement of iron-derived oxidative stress in the tumour development." (PMID 19785722, 2009). "Additionally, haptoglobin has been implicated in angiogenesis, the process by which new blood vessels form to supply the growing tumour with nutrients and oxygen." (PMID 40606553, 2025). "This complex glycosylation pattern makes haptoglobin particularly susceptible to altered glycosylation, which might influence tumor development and progression." (PMID 37876941, 2023). "These proteins (haptoglobin, ceruloplasmin, and hemopexin) are components of serum, suggesting that the large number of serum proteins in both the Pap test fluid and swab underlies the similarity of these samples relative to the tumor sample." (PMID 33413078, 2021). "By modulating the balance of reactive oxygen species (ROS) in the tumour microenvironment, haptoglobin can influence endothelial cell function and blood vessel formation, facilitating tumour growth and metastasis." (PMID 40606553, 2025). "Consistent with previously research, our study also identified upregulation of genes (CP, HP and CYBA) associated with oxidative stress in moderately differentiated tumours." (PMID 40847563, 2025). "It has been shown that haptoglobin can alter cytokine profiles in the tumour microenvironment, promoting tumour growth and metastasis." (PMID 40606553, 2025). "Haptoglobin’s capacity to suppress immune responses and its potential role in promoting tumour angiogenesis are key factors in its involvement in malignancy." (PMID 40606553, 2025). "The role of haptoglobin in malignancy is multifaceted, influencing both tumour progression and the microenvironment." (PMID 40606553, 2025). "In particular, haptoglobin’s anti-inflammatory effects can suppress immune surveillance, aiding in tumour immune evasion." (PMID 40606553, 2025). "A study showed that haptoglobin-knockout mice have more tumor masses, suggesting that acute-phase reactants inhibit tumorigenesis, possibly by suppressing inflammatory responses." (PMID 36718454, 2023). "ENPP1 promoted neutrophil extracellular trap (NET) formation via tumor cell expression of haptoglobin, supporting relapse and protecting the tumor from radiotherapy." (PMID 36910138, 2023). "Analysis of the contribution of lung and tumor microenvironment derived haptoglobin in cachexia serves as an area for future research." (PMID 38022578, 2023). "Recently, serum fucosylated haptoglobin (Fuc-Hp) was thought to play an important role in tumour immunity in several types of cancer." (PMID 37821468, 2023). "The Hb moiety of this nano system can preferentially target the M2-type TAMs via the CD163 surface receptor and bind to endogenous plasma haptoglobin (Hp), thereby killing tumor cells." (PMID 36338748, 2022). "Similar anti-tumor and immunomodulatory effects were also reported in mice bearing hepatoma or sarcoma tumors with the administration of recombinant HP-NAP fused with maltose binding protein (rMBP-NAP)." (PMID 36613542, 2022). "Administration of recombinant HP-NAP in mice reduced the growth of bladder cancer by triggering tumor necrosis and inducing a strong Th1 cytotoxic response both within tumors and local lymph nodes." (PMID 36613542, 2022). "Haptoglobin showed a significantly high expression in tumor samples compared to healthy controls (p = 0.0006) by western blotting." (PMID 32620920, 2020). "Haptoglobin was reported to have activities of anti-inflammatory, anti-oxidant, autoimmune and tumor angiogenesis." (PMID 27248178, 2016). "The role of haptoglobin in recruiting tumor cells to a defined niche was validated using an animal model of human metastatic breast cancer." (PMID 26634905, 2015).